TNNI3K (TNNI3 interacting kinase)
Diseases named in the same sentence as TNNI3K in open-access papers (continued):
Sharing a sentence is not in itself a finding about the gene and the disease.
heart failure (6 papers, 2009 to 2023). Inability of the heart to pump blood at an adequate rate to meet tissue metabolic requirements. "TNNi3K is selectively expressed in heart tissues and has been linked to cardiac hypertrophy dilated cardiomyopathy, pressure overload-induced heart failure, and ischemia/reperfusion injury in an in-vivo neonatal rat model." (PMID 32272798, 2020). "Here we report the molecular characterization of allelic variation at the murine Tnni3k gene, and present in vivo functional evidence showing that Tnni3k underlies the heart failure modifier locus, Hrtfm2." (PMID 19763165, 2009). "In a double transgenic heart failure mouse model expressing both Calsequestrin (Csq) and TNNI3K (TNNI3Ktg/Csqtg), TNNI3K was identified as a modifier of disease severity." (PMID 34203974, 2021). "TNNI3K expression also accelerates disease progression in a pressure-overload model of heart failure." (PMID 19763165, 2009). "Discovery of Tnni3k as a modifier of murine heart failure identifies it as a candidate for development of drugs to treat heart failure." (PMID 19763163, 2009). "TNNi3K inhibitor development could serve the purpose of developing novel heart failure therapeutics and probing biological function of TNNi3K." (PMID 32272798, 2020). "As the phosphorylation state of Ser22 and/or Ser23 is significantly reduced in end-stage failing hearts, future studies investigating whether TNNI3K could be a potential therapeutic target for heart failure should be pursued." (PMID 23472207, 2013). "As with the renin-angiotensin and β-adrenergic systems, inhibition of which are mainstays of current heart failure therapy, Tnni3k may participate in adaptive stress responses that become deleterious in pathological conditions such as heart disease." (PMID 19763163, 2009). "Taking advantage of these resources, Wheeler and colleagues provide in this issue of PLoS Genetics compelling evidence that a little-studied, cardiac-specific protein kinase, cardiac Troponin I-interacting kinase (Tnni3k), is a strong modifier of the development of heart failure." (PMID 19763163, 2009). "TNNI3K could be a potential therapeutic target for preventing from heart failure." (PMID 23472207, 2013). "First, while transgenic expression of Tnni3k in a largely DBA background did not affect heart function or survival in control mice, it markedly accelerated heart failure in CSQ transgenic mice." (PMID 19763163, 2009).
viral myocarditis (5 papers, 2009 to 2026). Myocarditis that is caused by an infection with a viral agent. "The locus including both TNNI3K and FPGT genes was found to be responsible for susceptibility to viral myocarditis in mice." (PMID 23915065, 2013). "Hence, the authors suggested that viral myocarditis is regulated by Tnni3k or Fpgt via affecting myocardial integrity or cellular immune response, respectively." (PMID 34203974, 2021).
Arrhythmia (4 papers, 2021 to 2023). Any cardiac rhythm other than the normal sinus rhythm. "A recent analysis proved that TNNI3K had direct interactions with three DCM‐linked sarcomeric proteins (viz, myosin‐binding protein C, troponin I and cardiac α‐actin); therefore, the loss of function of TNNI3K resulted in myocardial structural disorders and arrhythmias." (PMID 37183561, 2023). "Altogether, these data suggest that TNNI3K nonsense variants might only be susceptibility factors for conduction abnormalities or arrhythmias but are not causal per se." (PMID 33664309, 2021).
atrial fibrillation (2 papers, 2023 to 2025). A disorder characterized by an electrocardiographic finding of a supraventricular arrhythmia characterized by the replacement of consistent P waves by rapid oscillations or fibrillatory waves that vary in size, shape and timing and are accompanied by an irregular ventricular response. "In the UK Biobank, we observed an association between TNNI3K missense (but not loss-of-function) variants and DCM and atrial fibrillation." (PMID 37199186, 2023).
depression (2 papers, 2021 to 2025). "In addition, combined with previous genome-wide association studies on depression, a correlation was found between the levels of Tnni3k and Tbx1 in the hippocampus and RIB induced depressive-like behavior." (PMID 33531473, 2021).
heart attacks (2 papers, 2015 to 2023). "In mouse models, TNNI3K expression has been linked to cardiac function and cardiac oxidative stress following myocardial infarction." (PMID 26537541, 2015).
arrhythmogenic right ventricular cardiomyopathy (1 paper, 2023). "For instance, the L513P variant, identified in a young patient with arrhythmogenic right ventricular cardiomyopathy (ARVC), was found to be associated with a decrease in the levels of TNNI3K’s mRNA and protein." (PMID 37628941, 2023).
cardiac ischemia (1 paper, 2009). "In a murine model of cardiac ischemia, intramyocardial transplantation of Tnni3k-overexpressing P19CL6 cells promoted cardiomyogenesis and improved cardiac function." (PMID 19763165, 2009).
diabetic cardiomyopathy (1 paper, 2023). Diabetic cardiomyopathy is a disorder of the heart muscle in people with diabetes. "We performed PPI network analysis using Tnni3k and its correlated genes involved in the top five pathways (insulin resistance, diabetic cardiomyopathy, AGE-RAGE signaling pathway in diabetic complications, adrenergic signaling in cardiomyocytes, and TGFβ signaling)." (PMID 37628941, 2023).
Hyperglycemia (1 paper, 2023). An increased concentration of glucose in the blood. "The current study evaluated changes in embryonic heart development and the expression levels of sarcomeric proteins (troponin I, desmin, and TNNI3K), junctional proteins, glucose transporter-1, and Ki-67 under fetal hyperglycemia." (PMID 36983924, 2023). "Following hyperglycemia exposure, TNNI3K expression was upregulated by 30% in the right ventricular wall (p = 0.003), 37% in the left ventricular wall (p = 0.002), and 34% in the interventriucular septum (p = 0.002) of the HG group compared to the corresponding tissues from the NT group." (PMID 36983924, 2023). "Embryo-fetal hyperglycemia may trigger an increase in the expression levels of TNNI3K and troponin I, as well as dysfunction of occlusive and adherent junctions, ultimately inducing abnormal cardiac remodeling." (PMID 36983924, 2023).
Hypertension (1 paper, 2022). The presence of chronic increased pressure in the systemic arterial system. "Inhibition of RNPEP was shown to suppress hypertension in spontaneously hypertensive rats, and inhibition of TNNI3K and PDE5A was shown to be associated with suppressed contractility." (PMID 35172813, 2022).
Insulin resistance (1 paper, 2023). Increased resistance towards insulin, that is, diminished effectiveness of insulin in reducing blood glucose levels. "Expression levels of Tnni3k significantly correlated with multiple cardiac (heart rate, wall thickness, PR duration, and T amplitude) and metabolic (glucose levels and insulin resistance) phenotypes in BXDs." (PMID 37628941, 2023). "Further, we identified Nfkb1 to be significantly correlated with Tnni3k- and Tnni3k-correlated genes involved in both, cardiac and insulin resistance-related pathways." (PMID 37628941, 2023).
myocarditis (1 paper, 2009). Myocarditis is a condition that is characterized by inflammation of the heart muscle (myocardium). "Assuming that Tnni3k also underlies the Vms1 locus, viral-induced myocarditis might represent another disease context where expression of TNNI3K is protective." (PMID 19763165, 2009).
Sepsis (1 paper, 2021). Sepsis is defined as life-threatening organ dysfunction caused by a dysregulated host response to infection. "The aim of this study was to investigate the effect of cardiac troponin I-interacting kinase (TNNI3K) on sepsis-induced myocardial dysfunction (SIMD) and further explore the underlying molecular mechanisms." (PMID 34136567, 2021). "Herein, the aim of this study was to establish a rat model of sepsis treatment with LPS to investigate the effect of TNNI3K on SIMD." (PMID 34136567, 2021).
ventricular tachycardia (1 paper, 2023). A disorder characterized by an electrocardiographic finding of three or more consecutive complexes of ventricular origin with a rate greater than a certain threshold (100 or 120 beats per minute are commonly used). "Of note, also the p.Ile512Phe variant (ie, at the same position as the p.Ile512Thr variant) identified in 2 independent probands with DCM and ventricular tachycardia demonstrated increased TNNI3K autophosphorylation in vitro." (PMID 37199186, 2023).
heart disease (10 papers, 2009 to 2025). "High levels of TNNI3K are associated with slower conduction, faster progression of cardiac disease, and worse recovery after reperfusion injury, whereas reduced TNNI3K levels showed beneficial cardiac effects." (PMID 34203974, 2021). "The first paper that associated TNNI3K with cardiac disease describes a multi-generation family carrying a missense variant in TNNI3K (c.1577G>A) co-segregating with atrial tachyarrhythmia, CCD, and DCM." (PMID 34203974, 2021). "These compounds were found to also inhibit B-Raf kinase, which is structurally comparable to TNNI3K and has also been linked to several cardiac diseases." (PMID 34203974, 2021). "In recent years, the multiple roles of TNNI3K in cardiac disease and its therapeutic possibilities have been investigated." (PMID 39635265, 2024). "Despite previous reports in families and extensive work in mice, many questions remain about the effects of genetic variations in TNNI3K on cardiac disease and the direction of effects." (PMID 37199186, 2023). "Although the exact molecular mechanisms need to be further clarified, these findings in mice convincingly showed that the TNNI3K plays an important role in cardiac disease." (PMID 35274013, 2022). "These drugs are useful leads to define the cardiac biology of TNNI3K and are promising as a new approach in targeted cardiac diseases." (PMID 34203974, 2021). "In an in vitro kinase assay, we show that several common human TNNI3K kinase domain variants substantially compromise kinase activity, suggesting that TNNI3K may influence human heart regenerative capacity and potentially also other aspects of human heart disease." (PMID 31589606, 2019). "In either scenario, TNNI3K appears to play a critical role in modulating disease progression and outcome in heart disease." (PMID 19763165, 2009). "Together, we generated a unique zebrafish animal model of TNNI3K-based cardiac diseases and identified the Mypt1/Mlc2/Yap1/Nfatc1 axis as its downstream phosphorylation targets that could be potentially leveraged to develop new therapeutic strategies." (PMID 39926332, 2025). "However, the evidence linking TNNI3K to human cardiac disease has thus far remained limited to family reports, some with limited genetic evidence." (PMID 37199186, 2023). "The cardiac-specific expression of TNNI3K and its established role in murine cardiac physiology have prompted a great interest in the modulation of TNNI3K expression as a potential therapeutic strategy for heart disease." (PMID 35274013, 2022). "We here reviewed the role of TNNI3K in the scope of cardiac diseases in mice and humans." (PMID 34203974, 2021). "In addition, we review the potential of TNNI3K as a target for clinical treatments in different cardiac diseases." (PMID 34203974, 2021). "Tnni3k therefore provides a unique opportunity to understand the genetic basis of CM polyploidization in a way that has natural correlates and potentially also influences human heart disease." (PMID 31589606, 2019). "Significant additional work will be required to formally demonstrate that Tnni3k activity modulates progression of human heart disease, but two sets of data suggest that the results may be relevant." (PMID 19763163, 2009). "TNNI3K may be an ideal candidate for the development of small molecule kinase inhibitors for categories of heart disease where TNNI3K expression is detrimental." (PMID 19763165, 2009). "Tnni3k exacerbated cardiac dysfunction in this pressure-overload model, thereby providing important evidence that Tnni3k regulates development of heart disease in a model that may be physiologically more directly relevant to human heart disease." (PMID 19763163, 2009). "These combined data demonstrate that Tnni3k plays a critical role in the modulation of different forms of heart disease, and this protein may provide a novel target for therapeutic intervention." (PMID 19763165, 2009).
heart disease (continued). "We next sought to determine whether TNNI3K variants contribute to cardiac diseases in the general population, without the inclusion bias inherent to a cohort referred for genetic testing." (PMID 37199186, 2023). "However, II‐14 died of heart disease at an early age and over half of previously reported families had a history of sudden cardiac death (SCD), which indicated that TNNI3K mutation may have connections with high risk of SCD." (PMID 32529721, 2020). "Further investigation of TNNI3K function in these and other cardiomyopathic mouse models will lead to increased understanding of its role in both normal and pathological contexts, and may provide a novel target for therapy for heart disease." (PMID 19763165, 2009). "Therefore, TNNI3K may be a potential target for the treatment of different cardiac diseases." (PMID 39635265, 2024). "The role of haploinsufficiency of TNNI3K in cardiac disease is thus far unclear due to a lack of large families and the presence of such variants in the general population." (PMID 34203974, 2021).
cardiovascular disease (4 papers, 2015 to 2023). "To date, there are only four mutations in TNNI3K that have been found to be relevant with cardiovascular diseases, including three missense mutations and one splicing mutation." (PMID 32529721, 2020). "Cardiovascular disease caused by the TNNI3K mutation is an autosomal dominant disease, which means individuals will have the disease if only one chromosome carries the mutant allele." (PMID 32529721, 2020). "Interaction partners of TNNI3K embody cardiac troponin I (cTnI), anti‐oxidant protein 1 (AOP‐1), and p38, which make TNNI3K an important factor in cardiovascular diseases." (PMID 32529721, 2020).
cancer (2 papers, 2016 to 2018). A tumor composed of atypical neoplastic, often pleomorphic cells that invade other tissues. "A selective inhibitor of TnI-interacting kinase 3 exists and may be useful for dissecting potential TNNI3K-dependent signaling pathways in cancer cells." (PMID 29416706, 2018). "Further studies should aim to confirm the expression of TNNI3K at the protein level in human cancer cells, determine the subcellular localization of this kinase, and ascertain whether it may play a role in malignant cell growth." (PMID 29416706, 2018).
infection (1 paper, 2013). The state of being infected such as from the introduction of a foreign agent such as serum, vaccine, antigenic substance or organism. "In cultured cardiomyocytes, infection with Ad-TNNI3K significantly induced cTnI phosphorylation at Ser22/Ser23 on the basal and isoproterenol-stimulated level, relative to cells infected with Ad-GFP." (PMID 23472207, 2013).
TNNI3K also shares sentences with these, for which no sentence is quoted: cardiac arrhythmias (2 papers); hypertrophic cardiomyopathy (2); Supraventricular tachycardia (2); atrial tachycardia (1); atrioventricular-nodal reentry tachycardia (1); channelopathies (1); conduction disorder (1); diabetes (1); Epileptic encephalopathy (1); ischemic cardiomyopathy (1); rheumatoid arthritis (1); Right ventricular cardiomyopathy (1); Type 2 diabetes (1); Ventricular arrhythmia (1); Ventricular hypertrophy (1); viral infection (1).